CEP170 (centrosomal protein 170)
Description:
Plays a role in microtubule organization. Required for centriole subdistal appendage assembly.
Synonyms: FAM68A; KAB; KIAA0470
Tractability: PROTAC: ubiquitination databases record sites on it; its protein half-life has been measured.
Gene: Protein-coding gene on chromosome 1 (243,124,428 to 243,255,793, reverse strand). Ensembl gene ENSG00000143702.
Subcellular location: Cytoplasm, cytoskeleton, microtubule organizing center, centrosome; Cytoplasm, cytoskeleton, microtubule organizing center, centrosome, centriole; Cytoplasm, cytoskeleton, spindle
Subcellular location (Human Protein Atlas): Basal body; Centrosome; Cytosol
Gene Ontology:
Molecular function: protein binding
Cellular component: centriolar subdistal appendage; centriole; centrosome; ciliary basal body; spindle
Genetic constraint (gnomAD): Loss-of-function variants: 21 observed, 115.98 expected, observed/expected ratio (o/e) 0.18, 90% interval 0.13 to 0.26. The synonymous counts are far from expectation, so gnomAD's model fits this gene poorly and the ratio says little. Missense variants: 899 observed, 1,536.7 expected, observed/expected ratio (o/e) 0.59, 90% interval 0.55 to 0.62. Synonymous variants: 326 observed, 516.33 expected, observed/expected ratio (o/e) 0.63, 90% interval 0.58 to 0.69.
Homologues: Orthologues: chimpanzee CEP170 (99% identical), rabbit CEP170 (94% identical), dog CEP170 (93% identical), macaque CEP170 (93% identical), pig CEP170 (92% identical), mouse Cep170 (89% identical), rat Cep170 (88% identical), tropical clawed frog cep170 (59% identical), zebrafish cep170aa (49% identical). Paralogues in human: CEP170B (32% identical).
Diseases named in the same sentence as CEP170 in open-access papers:
CEP170 is named in the same sentence as 17 diseases in open-access papers, as found by Europe PMC text mining. Sharing a sentence is not in itself a finding about the gene and the disease. The quoted sentences say what the papers report.
multiple myeloma (7 papers, 2022 to 2025). "In myeloma, ac4C acetylation is involved in modulating the stability and translation efficiency of centrosomal protein 170 (CEP170) mRNA, thus promoting its expression." (PMID 41316475, 2025). "NAT10 improved the translation efficiency of CEP170 by acetylating CEP170 mRNA, which regulating CEP170 during cell mitosis to influence in multiple myeloma progression." (PMID 40588654, 2025). "Overexpression of CEP170 was found to promote cell proliferation and chromosomal instability in multiple myeloma." (PMID 40881352, 2025). "For example, NAT10 acetylates CEP170 mRNA to enhance CEP170 translation efficiency and leads to myeloma growth, and NAT10 promotes cisplatin chemoresistance in bladder cancer cells by enhancing DNA damage repair (DDR)." (PMID 39246323, 2024). "A recent study has demonstrated that NAT10 enhances the translation efficiency of CEP170 by acetylating its mRNA, thereby promoting the proliferation of multiple myeloma cells." (PMID 38459019, 2024). "In addition, NAT10 promotes the proliferation of multiple myeloma (MM) cells by acetylating CEP170 mRNA, which increases its translation efficiency." (PMID 41316475, 2025). "BUB1B evokes chromosomal instability via phosphorylation of CEP170 to promote myeloma malignancy." (PMID 41163302, 2025). "Similarly, in multiple myeloma, acRIP-seq combined with ribosome profiling sequencing (Ribo-seq) confirmed CEP170 as a critical downstream target of NAT10." (PMID 40881352, 2025). "In this region it interacts with native centrosomal protein 170 (CEP170) to attenuate mutant CEP170 expression in MM cells, promoting multiple myeloma (MM) by inducing chromosomal instability and bone lesion formation, exerting a similar function to full-length CHEK1." (PMID 34996480, 2022).
breast carcinoma (1 paper, 2025). "NAT10 promotes cell proliferation in breast cancer by acetylating CEP170 mRNA to increase its translation efficiency." (PMID 41310903, 2025).
chlamydial infection (1 paper, 2015). "Moreover, it is known that CEP170 is phosphorylated through Polo-like kinase 1; but how the phosphorylation of CEP170 is involved in the formation or activities of the IPAM–CEP170 complex or influences chlamydial infection remains unknown." (PMID 26220855, 2015).
tumor (3 papers, 2015 to 2022). "Cells with de novo centrosome amplification should have a single CEP170-positive centrosome, whereas tumor cells with multiple CEP170-positive centrosomes are more consistent with doubling events, in which two mature centrosomes would be inherited." (PMID 26832928, 2016). "Our finding that TBK1 functions are necessary for mitosis suggests that the dependency of mutant K-Ras tumour cells on TBK1 for cellular transformation also reflects its roles in directing progression through mitosis, by targeting PLK1 as well as other targets like CEP170 and NuMA." (PMID 26656453, 2015).
cancer (1 paper, 2021). A tumor composed of atypical neoplastic, often pleomorphic cells that invade other tissues. "CEP170 plays an important role in microtubule organization and microtubule stability, and aberrant microtubule stability triggers defects in mitosis, leading to CIN in cancer cells." (PMID 34090465, 2021).
infection (1 paper, 2015). The state of being infected such as from the introduction of a foreign agent such as serum, vaccine, antigenic substance or organism. "Given that CEP170 is a key determinant of MT organization during infection, we next examined MT regrowth to assess the dynamics of this mechanism." (PMID 26220855, 2015). "However, after infection with C. trachomatis, simultaneous CEP170 knockdown resulted in rounding of the infected cells, whereas infected control siRNA cells remained elongated at both 48 h and 66 h." (PMID 26220855, 2015). "Consistent with the in vitro interaction and the effects of IPAM90-268 in cultured cells, colocalization of IPAM and CEP170 was observed at the inclusion, although – as might be expected during infection – both IPAM and CEP170 were additionally present in isolation." (PMID 26220855, 2015). "CEP170 knockdown remained stable for the duration of the infection cycle, and did not significantly influence the early phase (<24 h) of bacterial development in cultured cells." (PMID 26220855, 2015). "Indeed, these additional functions highlighted by studying infection could indicate dormant or incompletely understood roles for CEP170 in uninfected non-dividing cells." (PMID 26220855, 2015).
CEP170 also shares sentences with these, for which no sentence is quoted: bladder cancer (1 paper); chronic myelogenous leukemia (1); diabetes (1); esophageal cancer (1); glioma (1); Intellectual disability (1); microcephaly (1); neurodevelopmental disorder (1); ovarian carcinoma (1); primordial dwarfism (1); schizophrenia (1).